CEACAM1 (CEA cell adhesion molecule 1)
Diseases named in the same sentence as CEACAM1 in open-access papers (continued):
Sharing a sentence is not in itself a finding about the gene and the disease.
Insulin resistance (continued). "Ceacam1 is related with insulin resistance, and its liver-specific deletion can lead to chronic hyperinsulinemia, impaired insulin clearance, hepatic insulin resistance and steatosis." (PMID 34692767, 2021). "A decrease in CEACAM1 has been found to be a marker of insulin resistance, with its overexpression having been shown to reverse insulin resistance." (PMID 31805072, 2019). "The progressive decrease in hepatic Ceacam1 mRNA stems from a compromised ability of insulin to induce Ceacam1 transcription under conditions of hyperphagia-driven insulin resistance and from PPARα activation by lipolysis-derived fatty acids." (PMID 31266142, 2019). "The progression of insulin resistance in age-dependent manner in Cc2−/− males appears to involve the differential reduction of CEACAM1 in the hypothalamus as well as in the liver." (PMID 31266142, 2019). "The hepatic insulin resistance likely results from impaired CEACAM1-dependent hepatic insulin clearance pathways and resultant chronic hyperinsulinemia." (PMID 31266142, 2019). "Our real-time PCR analysis of hyperglycemic HepG2 cells reveal suppression of CEACAM1 as compared to normoglycemic HepG2 cells, which suggests insulin resistance as a result of hyperglycemia and serves as a link to obesity and NAFLD." (PMID 31805072, 2019). "Together, this assigns a significant role for reduced hepatic CEACAM1 levels in hyperinsulinemia-driven metabolic abnormalities, including insulin resistance and hepatic steatosis in mice." (PMID 28396653, 2017). "Conversely, transgenically protecting hepatic CEACAM1 in L-CC1 mice prevented diet-induced insulin resistance and limited hepatic steatosis in response to HF diet." (PMID 26284027, 2015). "Phenocopying global Ceacam1 null mice (Cc1–/–), C57/BL6J mice fed a high-fat (HF) diet exhibited reduced hepatic CEACAM1 levels and impaired insulin clearance, followed by hyperinsulinemia, insulin resistance, and visceral obesity." (PMID 26284027, 2015). "The studies that have focused on CEACAM1 related to insulin resistance have mainly been done on experimental animal models and using molecular biologic methods." (PMID 21569294, 2011). "The CEACAM1-dependent endocytosis of insulin-bound insulin receptors facilitates the degradation of insulin and maintains the normal insulin half-life in the circulation, thereby preventing hyperinsulinemia and systemic insulin resistance." (PMID 40985048, 2025). "Additionally, the same investigation demonstrated that the rescue of CEACAM1 expression via adenovirus reversed high-fat-induced insulin resistance and liver steatosis in mice." (PMID 40985048, 2025). "Deleting CEACAM1 exclusively in hepatocytes (as in AlbCre+Cc1fl/fl mice) impaired hepatic insulin clearance at 2–3 months of age, followed by hyperinsulinemia-driven hepatic insulin resistance and steatosis at ~6 months of age." (PMID 39640841, 2024). "This advanced phenotype is prevented by rescuing CEACAM1 in the liver, providing further in vivo demonstration of the critical role that CEACAM1-dependent insulin clearance pathways play in the pathogenesis of hepatic insulin resistance and NAFLD/NASH." (PMID 36009446, 2022). "In addition, the Ceacam1−/− mouse model is appropriate since these mice exhibit insulin resistance, metabolic disease and cardiomyopathy." (PMID 36559027, 2022). "As abdominal obesity and insulin resistance progress, the pulsatility of insulin release decreases, leading to defective insulin signaling in hepatocytes, including CEACAM1 phosphorylation and, subsequently, reduction in hepatic insulin clearance to contribute to chronic hyperinsulinemia." (PMID 36009446, 2022). "CEACAM1, a transmembrane protein acting in hepatocytes to get rid of insulin excess hence limiting insulin resistance, has been shown to be lower in T1D and could be the link between NAFLD and T1D." (PMID 36531463, 2022).
Insulin resistance (continued). "Consistently, mice with global and liver-specific null deletion of Ceacam1 gene and with its liver-specific inactivation exhibited hyperinsulinemia with resultant insulin resistance, elevated hepatic lipid production, and redistribution to white adipose tissue to contribute to visceral adiposity." (PMID 34440862, 2021). "So far, the liver CEACAM1 knockout mice provide an in vivo proof of the key role of impaired hepatic insulin clearance and hyperinsulinemia in the pathogenesis of secondary hepatic insulin resistance." (PMID 33477364, 2021). "During gestation the level of CEACAM1 is being gradually increased, nevertheless, the GDM complication is typically manifested in increasing insulin resistance which may be caused by a significant deficiency of CEACAM1." (PMID 32326243, 2020). "In accordance with our results, earlier studies on experimental animal models reported that mice with null deletion of CEACAM1 or with liver-specific inactivation of CEACAM1 subsequently developed chronic hyperinsulinemia, insulin resistance, hepatic steatosis and visceral obesity." (PMID 32414367, 2020). "Similarly, transgenic overexpression of CEACAM1 in liver protects against diet-induced insulin resistance, visceral obesity, hepatosteatosis, and fibrosis in adipose tissue." (PMID 28396653, 2017). "Thus, a CEACAM1-targeted therapeutic approach could constitute an effective strategy against hepatic fibrosis while it ameliorates insulin resistance in patients with this metabolic abnormality." (PMID 39640841, 2024). "Our focus on CEACAM1 phosphorylation by the insulin receptor and its role in insulin clearance has provided a mechanistic underpinning for how reduced insulin clearance can cause insulin resistance and is not just a consequence thereof." (PMID 36009446, 2022). "Because endothelial cell injury precedes atherosclerosis, we herein investigated whether the loss of endothelial Ceacam1 initiates atheroma formation in the absence of insulin resistance." (PMID 35457157, 2022). "Similarly, treatment of HF-fed wild-type mice with exenatide, a long-acting glucagon-like peptide-1 receptor agonist that stimulates insulin secretion, prevented diet-induced insulin resistance and altered metabolism by restoring hepatic CEACAM1 expression via a PPARγ-dependent pathway." (PMID 30314283, 2018). "ROS and CEACAM1 activity are important factors to understand NAFLD development in individuals suffering from the metabolic syndrome (obesity, insulin resistance, T2D)." (PMID 37511031, 2023). "In this study, we chose the Ceacam1−/− model that develops NAFLD, insulin resistance, obesity and CVD in male Ceacam1−/− mice on normal chow starting at the age of 12–15 weeks and progressing to overt symptoms by ages >20 weeks." (PMID 36559027, 2022). "Global and liver-specific CEACAM1 null mice, and the liver-specific dominant-negative phosphorylation-defective S503A CEACAM1 (L-SACC1) mutants develop secondary insulin resistance due to chronic hyperinsulinemia." (PMID 34948019, 2021). "In addition, CEACAM1 controls insulin clearance to protect against insulin resistance, obesity, WAT-associated inflammation, hepatosteatosis (NAFLD), NASH, fibrosis and cardiovascular disease, as bolstered by observations in mice with global deletion of CEACAM1 expression." (PMID 30314283, 2018). "Mice lacking CEACAM1 (Cc1−/−) develop hyperinsulinemia, insulin resistance, and steatohepatitis, along with early fibrosis." (PMID 40699685, 2025).
Insulin resistance (continued). "This study also showed that mice with an HSC-specific CEACAM1 knockout displayed hepatic inflammation and fibrosis but without insulin resistance or hepatic steatosis." (PMID 40985048, 2025). "In CEACAM1 null mice, the absence of CEACAM1 led to an inability to clear insulin, leading to hyperinsulinemia followed by insulin resistance, obesity, and non-alcoholic steatohepatitis." (PMID 36741860, 2023). "Since CEACAM1 plays a crucial role in insulin resistance and in NAFLD development, we can hypothesize that pharmacologically upregulating CEACAM1 could be a promising therapeutic approach for the treatment of NAFLD in T1D." (PMID 36531463, 2022). "Of note, htgCB1 mice displayed down-regulation of IDE and its proteolytic activity, but unaltered levels of phosphorylated carcinoembryonic antigen-related cell adhesion molecule 1 (CEACAM1), in parallel with hepatic insulin resistance, lower insulin clearance and moderate hyperinsulinemia." (PMID 33477364, 2021). "Suppression of CEACAM1, GLUT2, and PON1, and elevation of CD36, PCK1, and G6PK were also found to be characteristic in hyperglycemic HepG2 cells compared with normoglycemic cells, suggesting insulin resistance and NAFLD." (PMID 31805072, 2019). "In addition, high-fat diet diminished CEACAM1 expression and induced impaired insulin clearance, hyperinsulinemia and insulin resistance in C57/BL6J mice, and these effects were counteracted by liver-specific inducible CEACAM1 expression." (PMID 28469173, 2017). "Consistent with the finding that reduction of hepatic CEACAM1 plays a critical role in diet-induced altered metabolic response, transgenic protection of hepatic CEACAM1 in L-CC1 mice prevents hyperinsulinemia, insulin resistance, and hepatosteatosis in response to high-fat diet." (PMID 28184213, 2017). "Recent reports from our laboratories show that high-fat diet progressively reduces hepatic CEACAM1 level in C57BL/6J mice until it reaches >50% after 3 weeks, at which point, insulin clearance is impaired and hyperinsulinemia develops with attendant hepatic insulin resistance and steatohepatitis." (PMID 28184213, 2017). "So, the higher incidence of a decreased CEACAM1 expression in severely obese non-diabetic group than non-obese non-diabetic group reflects the possible association between a decreased hepatic CEACAM expression and insulin resistance." (PMID 21569294, 2011). "Male Ceacam1−/− mice that develop NAFLD, insulin resistance and CVD on normal chow are a potential model for studying the dysregulation of fatty acid uptake." (PMID 36559027, 2022).
Hyperinsulinemia (25 papers, 2014 to 2026). An increased concentration of insulin in the blood. "Whereas the loss of Ceacam1 by <50% promotes fatty acid β-oxidation, its progressive loss by >50% (after about 3–4 weeks) represses hepatic insulin clearance to cause chronic hyperinsulinemia and ensuing hepatic steatosis and hepatic insulin resistance." (PMID 36009446, 2022). "High-fat diet represses hepatic CEACAM1 levels to impair insulin clearance and cause hyperinsulinemia that in turn, drives increased hepatic lipid production and output to the white adipose depot for storage." (PMID 28184213, 2017). "Hyperinsulinemia in LCR rats is associated with impaired hepatic insulin clearance in correlation with reduced Ceacam1 mRNA and protein levels." (PMID 28396653, 2017). "When the loss of hepatic CEACAM1 reaches more than 50% and impairment of insulin clearance develops, chronic hyperinsulinemia followed by hepatic steatosis ensues." (PMID 28396653, 2017). "Obese Zucker and Koletsky hyperphagic obese rats display a decline in their hepatic CEACAM1 content likely causing impaired insulin clearance and hyperinsulinemia." (PMID 28396653, 2017). "Moreover, hyperinsulinemia caused by deleting CEACAM1 in hepatocytes induced the production of Endothelin-1, which transactivates EGFR via Src kinase, as we have shown." (PMID 39640841, 2024). "Combined, reduced hepatic CEACAM1 and hyperinsulinemia can cause hepatic steatosis." (PMID 34948019, 2021). "The link between insulin clearance and atherosclerosis is further underlined by findings from rodents: knockout of CEACAM1, the central protein for insulin clearance in the liver, causes hyperinsulinemia and marked endothelial dysfunction and formation of atherosclerotic plaques." (PMID 33384433, 2020). "Bolstering this function of CEACAM1, defective hepatic insulin clearance and subsequently, chronic hyperinsulinemia develops in mice with global null mutation (Cc1−/−) or with liver-specific overexpression of the dominant-negative phosphorylation-defective inactive isoform of Ceacam1 (L-SACC1)." (PMID 28396653, 2017). "Since hyperinsulinemia and reduced hepatic CEACAM1 can induce hepatic steatosis, thereby potentially amplifying the effect of oleate, we assessed hepatic fat content using oil-red-O staining." (PMID 34948019, 2021). "This is in contrast to the remarkable hyperinsulinemia-driven downregulation of insulin receptors in the hepatocytes of liver-specific inactive CEACAM1 mutants, as analyzed by Scatchard plot." (PMID 34440862, 2021). "Hyperinsulinemia and corruption of CEACAM1-mediated repression on hepatic fatty acid synthase (FASN) activity in hyperinsulinemia further support hepatic steatosis and SREBP1c-mediated lipogenesis and are accompanied by a reduction in hepatic β-oxidation." (PMID 30314283, 2018). "Consistent with a role for CEACAM1 in insulin clearance, obese rats display reduced insulin clearance (as measured by steady-state C-peptide/insulin molar ratio) and hyperinsulinemia." (PMID 28396653, 2017). "Caloric restriction reduces their hyperinsulinemia, and subsequently, hepatic fatty acid synthase level and steatosis, in parallel to inducing hepatic CEACAM1 levels and normalizing hepatic insulin extraction to the level of HCR." (PMID 28396653, 2017). "Together, this demonstrates that altered CEACAM1-dependent insulin clearance pathways drive hyperinsulinemia-mediated link of hepatic steatosis to visceral obesity and increased total fat mass." (PMID 28184213, 2017). "This is of particular importance, as the liver-specific inactivation of Ceacam1, characterized by hyperinsulinemia and glucose intolerance, results in decreased osteoclastogenesis." (PMID 25490771, 2014). "Additionally, systemic hyperinsulinemia and reduced hepatic insulin clearance—potentially due to decreased expression of carcinoembryonic antigen-related cell adhesion molecule 1 (CEACAM1) because of hepatic IR—further promote hepatic lipogenesis." (PMID 39605938, 2024).
Hyperinsulinemia (continued). "Carcinoembryonic antigen-related cell adhesion molecule 1 expression occurs preferentially in liver, and restoration of its function only at liver of null CEACAM-1 mice reverse the hyperinsulinemia and fatty liver deposition observed in global knockout CEACAM-1 model." (PMID 32850773, 2020). "Moreover, hyperinsulinemia in Ceacam1−/− mice induces hypothalamic FASN level and activity, which contributes to hyperphagia and physical inactivity." (PMID 30314283, 2018). "For example, the lack of CEACAM-1, a key protein enrolled in hepatic insulin clearance driving hyperinsulinemia, in the kidney leads to increased renin levels contributing to a potentiation of the RAS system and hypertension." (PMID 32850773, 2020). "Adenoviral-mediated reintroduction of intact wild-type CEACAM1 in hepatocytes protects against the adverse negative metabolic effects of a high-fat (HF) diet: These include hyperinsulinemia, hepatic lipid production and steatohepatitis." (PMID 30314283, 2018). "Hence, the described CEACAM-1 renal effects can be due to the lack of its expression as well as the observed hyperinsulinemia." (PMID 32850773, 2020). "Therefore, despite causing defective IR endocytosis in the liver, SHP2 inhibition led to a mild defect in insulin clearance, but not severe hyperinsulinemia as observed in the CEACAM1 KO mice." (PMID 30931927, 2019).
lung carcinoma (21 papers, 2006 to 2025). "The four genes with lung cancer-associated alternative splice forms newly identified in this study were: CEACAM1, FHL1, MLPH, and SUSD2." (PMID 20525254, 2010). "However, there are few reports concerning the diagnostic value of circulating CEACAM1 in lung cancer patients, although the early diagnosis of NSCLC is unsatisfactory." (PMID 23885995, 2013). "Paradoxically, CEACAM1 expression has been reported to be increased in several other cancers, including gastric cancer and nonsmall-cell lung cancer." (PMID 35812245, 2022). "CEACAM1 can be one of potential target candidates to play a critical role in the COPD-lung cancer transits." (PMID 31072323, 2019). "CEACAM1 mediates transcellular transcytosis, suppresses immune cell activities and inflammatory responses, and plays a critical role in the development of lung cancer and acute exacerbation of chronic obstructive pulmonary diseases (AECOPD)." (PMID 31072323, 2019). "It is therefore necessary to evaluate the changes in serum CEACAM1 in the context of lung cancer." (PMID 23885995, 2013). "Additionally, the CEACAM1 expression levels in lung cancer tissues together with adjacent normal lung tissues were verified at the mRNA level from the same serum providers in parallel using quantitative real-time PCR." (PMID 23885995, 2013). "Our data indicated that the serum levels of CEACAM1 could discriminate lung cancer patients from health donors and that CEACAM1 might be a useful marker in early diagnosis of NSCLC." (PMID 23885995, 2013). "Paraffin sections of lung tissues from 19 donors who underwent surgery for lung resection to treat lung cancer were stained with an IgG control antibody and antibodies specific for CEACAM1, 5 and 6, as well as with an antibody specific for CEACAM8, which is solely expressed in human granulocytes." (PMID 23941132, 2013). "In this study, we aimed to study whether CEACAM1 could discriminate lung cancer patients from health donors." (PMID 23885995, 2013). "Furthermore, elevated CEACAM1 expression correlates with severe disease and tendency to reduced cancer-related survival of the total population, rather indicating CEACAM1 as a promoter of lung cancer progression." (PMID 30406153, 2018). "However, little information exists concerning serum CEACAM1 in lung cancer." (PMID 23885995, 2013). "Finally, the expression of CEACAM1-1, CEACAM1-3, and CEACAM1-3A was determined in a panel of 23 lung cancer cell lines derived from tumors of all the major histological subtypes, which demonstrated the expression of these three isoforms not only in NSCLC but also in small cell lung cancer (SCLC)." (PMID 20525254, 2010). "CEACAM1, CEA/CEACAM5, and CEACAM6 are cell adhesion molecules (CAMs) of the carcinoembryonic antigen (CEA) family that have been shown to be deregulated in lung cancer and in up to 50% of all human cancers." (PMID 20090913, 2010). "Other genes that we chose (e.g., CD24, TACSTD1, TACSTD2, CEACAM1, and PRKCD) are correlated with lung carcinoma or other tumors." (PMID 19874631, 2009). "A recent study investigating non-cancer tissue sections taken from patients with lung cancer identified the clear expression of CEACAM5 as well as CEACAM1 and CEACAM6 family members in this non-cancer tissue." (PMID 28660319, 2017). "Our findings indicate that the combination of CEACAM1, TNFSF4, GEM, CD47, VTCN1, and TANlncSig in squamous cell carcinoma can effectively stratify patients by prognosis, highlighting these immune checkpoint receptors as potential therapeutic targets against advanced lung cancer." (PMID 36386809, 2022).